S100A11 (S100 calcium binding protein A11)
Diseases named in the same sentence as S100A11 in open-access papers (continued):
Sharing a sentence is not in itself a finding about the gene and the disease.
glioma (continued). "However, this relationship was only relevant for S100A11 expression in IDH mut gliomas and no conclusive evidence was obtained regarding the prognostic role of S100A13 in tumor progression." (PMID 39744679, 2025). "For the GEPIA-derived cohort, the expression levels of S100A11, S100A16, and S100B in low-grade glioma (LGG) and GBM samples increased compared with those in noncarcinoma samples, while S10013 in LGG tissue was upregulated in normal tissues." (PMID 34712325, 2021).
hepatocellular carcinoma (14 papers, 2004 to 2025). A malignant tumor that arises from hepatocytes. "Intriguingly, the progression of hepatocellular carcinoma (HCC) driven by PCK1 deficiency was suppressed by SAM supplement or S100A11 KO in vivo and in vitro." (PMID 37166978, 2023). "Further studies demonstrated that S100A11 is overexpressed in metastatic hepatoma cells, and S100A11 knockdown decreases hepatoma cells proliferation, migration, invasion and EMT progress by inhibiting AKT and ERK signaling pathways." (PMID 36860671, 2023). "Further experiments suggest that S100A11 promotes hepatoma cell metastasis by activating AKT and ERK signaling pathways and accelerating EMT progress." (PMID 36860671, 2023). "Moreover, in tail-vein models of lung metastasis in nude mice, fewer metastatic foci were observed in tissue sections of the lungs in PKO cells infected with lentiviral sgS100A11, illustrating that the lung metastatic potential of PCK1-deficient hepatoma cells could be facilitated by S100A11." (PMID 37166978, 2023). "Firstly, we used RT-qPCR assay to detect S100A11 mRNA expression in these hepatoma cells, and we found that S100A11 mRNA in HCCLM3 was significantly overexpressed than the other three low-metastatic cell lines." (PMID 36860671, 2023). "We showed that S100A11 KO significantly reduced tumor burden in PKO hepatoma cells, indicating that S100A11 depletion effectively inhibited tumor growth in vivo." (PMID 37166978, 2023). "To evaluate whether S100A11 enhances EMT in hepatoma cells, we used optical microscopy to identify the morphology changes in S100A11 knockdown and overexpression cells." (PMID 36860671, 2023). "To analyze whether S100A11 activates AKT or ERK signaling pathway in hepatoma cells, we detected the expression and phosphorylation of key proteins in the two signaling pathways." (PMID 36860671, 2023). "Using in vitro cell culture model, we demonstrated that S100A11 is overexpressed in metastatic hepatoma cells, knockdown of S100A11 decreases hepatoma cells proliferation, migration, invasion, and epithelial-mesenchymal transition process by inhibiting AKT and ERK signaling pathways." (PMID 36860671, 2023). "Conclusively, these data show that knockdown of S100A11 inhibits hepatoma cell proliferation." (PMID 36860671, 2023). "In hepatocellular carcinoma, S100A11 is involved in inflammation which may contribute to cancer development." (PMID 33931048, 2021). "Also, S100A11 is involved in the development of hepatocellular carcinoma through inciting inflammation, substantiating its pro-tumoral role." (PMID 35111196, 2021). "However, S100A11 is also reported to be a tumor suppressor in hepatocellular carcinoma cells and epidermal keratinocytes." (PMID 25780452, 2015). "In addition, experimental studies have shown that S100A11 is a migration-related protein in laryngeal squamous cell carcinoma, and is involved in the invasion of hepatocellular carcinoma cells." (PMID 25780452, 2015). "Using the same proteomics strategy, S100A11 was also reported to be up-regulated in metastatic hepatocellular carcinoma (HCC) tissues, and to rise in the expression level with the progression of colorectal cancer." (PMID 21342498, 2011). "To further investigate the detailed role of S100A11 in HCC progression and metastasis, we chose four different human hepatoma cell lines, including HCCLM3, HepG2, Hep3B, and Li-7, for further studies." (PMID 36860671, 2023). "In human hepatocellular carcinoma, EIF3C activated expression of S100A11 involved in EIF3C-exosome increased tube formation in angiogenesis." (PMID 37864150, 2023). "Moreover, S100A11/ANXA2 complex is overexpressed in stressed cells to maintain the integrity of the plasma membrane, which can be damaged by cancer cell migration in hepatocellular carcinoma (HCC)." (PMID 35752610, 2022).
colorectal cancer (11 papers, 2008 to 2025). A primary or metastatic malignant neoplasm that affects the colon or rectum. "The role of S100A11 in colorectal cancer cell proliferation, migration, and invasion was assessed in the context of USP14 knockdown." (PMID 40374593, 2025). "Collectively, these results suggest that S100A11 is critical for maintaining the proliferative and anti-apoptotic properties of colorectal cancer cells, emphasizing its potential as a therapeutic target." (PMID 40567612, 2025). "The levels of S100A11 expression tended to be clearly higher in all colorectal cancer tissues compared to normal tissues." (PMID 38842658, 2024). "Our next question is how overexpression of S100A11 gives benefits such as active proliferative and migrative abilities to colorectal cancer cells." (PMID 38842658, 2024). "In this study, we revealed that S100A11 is elevated in colorectal cancer cells, and the increased level is actively conducive to promoting proliferative and migrative outgrowth." (PMID 38842658, 2024). "The identified new pathway greatly helps to comprehend S100A11’s nature in colorectal cancers and others." (PMID 38842658, 2024). "The high expression of S100A11 in colorectal cancer cells was further confirmed by immunohistochemistry." (PMID 38842658, 2024). "Correlating with changes in these TCF target genes, colorectal cancer proliferation and migration were also enhanced by overexpression of catenins, but decreased by suppression of S100A11 expression." (PMID 38842658, 2024). "Owing to the relatively high expression nature of S100A11 in colorectal cancer cells, even in sparsely occupied conditions in culture, the machinery of S100A11 expression regulation in cancer cells at molecular levels is our next subject to clarify." (PMID 38842658, 2024). "To elucidate the role of S100A11 in colorectal cancer, we overexpressed and downregulated the expression of S100A11 in DLD-1 cells and analyzed the phenotypic changes in the cells." (PMID 38842658, 2024). "The aberrant expression of S100A11 has been identified in various malignancies but its functional roles and underlying mechanisms in colorectal cancer (CRC) have not been fully elucidated." (PMID 40374593, 2025). "Thus, we aimed to investigate S100A11 functions within cancer cells, primarily focusing on colorectal cancer cells, whose S100A11 is abundantly present in cells and still poorly studied cancer for the protein." (PMID 38842658, 2024). "Therefore, in this study, we aimed to clarify the unidentified role of S100A11 within cancer cells, typically focused on colorectal cancers, since S100A11 shows relatively high expression in this type of cancer." (PMID 38842658, 2024). "Next, we investigated whether S100A11 is involved in colorectal cancer progression by activating the TCF signaling pathway." (PMID 38842658, 2024). "Besides S100A4 and S100P, we confirmed that the expression of S100A11 is enhanced in colorectal cancer, so the high expression of S100A11 in colorectal cancer leads us to a prediction of the cancer progression state." (PMID 38842658, 2024). "Several studies have shown that S100A11 is upregulated in colorectal cancer tissue." (PMID 34563043, 2021). "S100A11 promotes invasion of colorectal cancer by regulating TGFβ/Smad signaling." (PMID 34663163, 2021). "S100A11 promotes the invasion and migration of HCC cells and is required for TGF-initiated EMT in colorectal cancer cells." (PMID 31703598, 2019). "Based on these reports, we hypothesized that S100A11 may regulate TCF promoter activity via interaction with γ-catenin and desmosome proteins, which play a role in colorectal cancer outgrowth." (PMID 38842658, 2024). "We confirmed that S100A11 was highly expressed in other same-leagues of cancer cells, DLD-1 and HT-29, and that S100A11 was not expressed in HEK293, a non-colorectal cancer cell line." (PMID 38842658, 2024).
lung cancer (11 papers, 2011 to 2023). A malignant neoplasm involving the lung. "Further investigations are warranted in order to elucidate the mechanisms by which S100A11 promotes the progression of lung cancer." (PMID 26544866, 2015). "The metastatic phenotype of lung cancer seems to be also related to altered levels of S100A11, a member of S100 family of proteins, which are small calcium-binding proteins that have been implicated in prognosis and risk of metastasis in several tumor types." (PMID 22229091, 2011). "Upregulation of S100A11 plays a major role in lung cancer progression." (PMID 29607329, 2018). "A previous study found that S100A11 promoted the proliferation of lung cancer cells." (PMID 25780452, 2015). "Thus, although S100A6 and S100A11 belong to the same family of proteins, they have opposite roles in lung cancer progression." (PMID 22229091, 2011). "Moreover, we also observed that the expression level of S100A11 was obviously upregulated in tumor tissues compared with noncancer tissues in COAD, OV, KIRC, UCEC, lung cancer, PAAD, HNSC, and GBM." (PMID 36605485, 2023).
bladder cancer (10 papers, 2009 to 2024). "On the other hand, S100A11 is considered to operate as a tumor suppressor in bladder cancer and the low expression of S100A11 is associated with patients with bladder cancer." (PMID 36860671, 2023). "S100A11 is reported to be associated with advanced tumor behavior and poor survival in bladder cancer." (PMID 33815482, 2021). "In bladder carcinoma and renal carcinoma, its expression is related to tumor suppression, and decreased expression of S100A11 has been associated with an increase in histopathological grade, poorer prognosis and decreased survival." (PMID 19691830, 2009). "However, this is not common in all cancer species, for example, low expression of S100A11 in bladder cancers is associated with poor survival in the patients." (PMID 29362358, 2018). "However, decreased expression of S100A11 has been reported in bladder cancer, and downregulation of S100A11 has been associated with bladder cancer progression." (PMID 25780452, 2015). "Intriguingly, there is a dualism in S100A11 expression behavior suggesting that S100A11 is also a potential tumor suppressor in distinct tumor entities as its down‐regulation correlates with development of bladder cancer." (PMID 38408765, 2024). "Expression of S100A11 can be up‐ or down‐regulated in colorectal carcinoma, pancreatic ductal adenocarcinoma, and hepatocellular carcinoma, or bladder cancer, respectively." (PMID 38408765, 2024). "However, previous studies demonstrated that S100A11 expression levels were reduced in tumors with higher malignant activity in kidney and bladder cancers." (PMID 26544866, 2015).
glioblastoma (9 papers, 2008 to 2024). The most malignant astrocytic tumor (WHO grade IV). "Tu et al35 found that S100A11 acts as an oncogene in glioblastoma through the S100A11/ANXA2/NF-κB positive feedback loop." (PMID 39128058, 2024). "From this analysis, we found ten DEGs specific to IDH1-wt glioblastoma, namely, S100A11, AC091932.2, PIGH, AC020910.5, RPS8P6, AC105339.6, AL589986.1, AL049874.3, CEBPD, and Z99496.1." (PMID 37568598, 2023). "Although s100a11 has not been previously linked to depression, s100a11 is upregulated in neurological and inflammatory diseases, including glioblastomas, amyotrophic lateral sclerosis, rheumatoid arthritis, and autoimmune encephalitis." (PMID 38350966, 2024). "Moreover, in glioblastoma cells, s100a11 was shown to activate NF-κB via annexin-2, and NF-κB in turn had a positive feedback effect to increase s100a11 expression." (PMID 38350966, 2024). "For example, S100A16 is elevated in grade I astrocytoma and S100A11 in glioblastoma." (PMID 18781180, 2008). "ANXA2 is regulated by CircADAMTS6, S100A11, and miR155HG in glioblastoma (GBM) and promotes the progression of GBM." (PMID 38658569, 2024). "It has been reported that S100A11 shows overexpression in many cancer types, including glioblastoma (GBM)." (PMID 34712325, 2021).
Hepatic steatosis (9 papers, 2021 to 2025). Steatosis is a term used to denote lipid accumulation within hepatocytes. "Hepatotropic AAV8 encoding shRNAs targeting S100A10 or S100A11 were used to downregulate these proteins specifically in the liver of mice fed a diet inducing hepatic steatosis, inflammation, and fibrosis and in a genetic mouse model of MASLD bearing hepatocyte-specific deletion of PTEN (LPTENKO)." (PMID 40841353, 2025). "There was a difference in the pattern of steatosis in FFC-LIE compared with FFC-scr mouse livers, with greater microvesicular steatosis, suggesting a role for S100A11 in hepatic steatosis." (PMID 41027000, 2025). "We discovered how a key protein S100A11 is regulated and drives progression of fatty liver disease, revealing a new target for future treatments." (PMID 41027000, 2025). "In one previous report, S100A11 overexpression was found to activate lipogenesis and autophagy, conversely resulting in increased lipid accumulation and hepatic steatosis in animals being fed a HFD." (PMID 35982710, 2022). "In any case, these studies do show that S100A11 can affect autophagy and lipid metabolism, and that it plays an important and complex role in fatty liver disease." (PMID 34179021, 2021). "Upregulation of DDAH1 may improve liver fibrosis and hepatic steatosis in obese mice by reducing the expression of S100A11." (PMID 40646803, 2025). "Finally, among the DEGs, some are also key regulators of hepatic lipid metabolism (e.g., PIK3R1, PPARG, S100A11), suggesting that alterations in TIA1 expression/activity also contribute to fatty liver disease development." (PMID 35406476, 2022).
ovarian carcinoma (9 papers, 2015 to 2025). A malignant neoplasm originating from the surface ovarian epithelium. "For the first time, we demonstrated that FBXW11 functions by modulating the S100A11-mediated DNA damage repair pathway to enhance ovarian cancer cells' susceptibility to PARPis." (PMID 40747341, 2025). "A CCK-8 assay revealed that the introduction of the S100A11 overexpression plasmid reduced the FBXW11-enhanced susceptibility of ovarian cancer cells to olaparib." (PMID 40747341, 2025). "In summary, our study confirms that FBXW11 promotes the susceptibility of ovarian cancer cells to PARPi via affecting S100A11-mediated DNA damage repair." (PMID 40747341, 2025). "Next, we investigated whether the association of S100A11 with FBXW11 promotes ovarian cancer cell sensitivity to olaparib." (PMID 40747341, 2025). "We subsequently demonstrated that FBXW11 enhances the vulnerability of ovarian cancer cells to PARPi through the regulation of S100A11-mediated DNA damage repair processes." (PMID 40747341, 2025). "The findings indicated that FBXW11 overexpression expedited the degradation of S100A11 in ovarian cancer cells." (PMID 40747341, 2025). "In ovarian cancer, S100A11 promotes tumor invasion and metastasis, and high S100A11 expression levels are associated with poor PFS and OS." (PMID 40747341, 2025). "In ovarian cancer, S100A11 facilitates carcinoma growth and dissemination, and high S100A11 expression correlates with worse PFS and overall survival (OS)." (PMID 40747341, 2025). "Specifically, S100A11 plays a central role in promoting the growth, invasion, and migration of ovarian cancer cells." (PMID 38339228, 2024). "For example, disruption of the annexin A1/S100-A11 complex enhanced the migration and clonogenic growth of ovarian cancer cells by modulating epithelial growth factor signaling." (PMID 31545917, 2019). "Collectively, these results indicated that S100A11 was involved in the regulation of ovarian cancer cell growth." (PMID 25780452, 2015). "The results demonstrated that the invasion and migration activity of HO8910 cells was greatly suppressed in the sh#2 cells when compared with the Ctrl and NC cells, indicating that S100A11 was able to promote the invasion and migration of ovarian cancer cells." (PMID 25780452, 2015). "In the present study, the expression levels of S100A11 were found to be significantly increased in the ovarian cancer cell lines." (PMID 25780452, 2015). "The results of the present study demonstrated that knockdown of S100A11 inhibited the proliferation and anchorage-independent growth of HO8910 cells, suggesting that S100A11 contributes to the growth of ovarian cancer cells." (PMID 25780452, 2015). "In conclusion, S100A11 is overexpressed in ovarian cancer cells and the knockdown of S100A11 suppresses the growth, invasion and migration of ovarian cancer cells." (PMID 25780452, 2015). "The present study demonstrated that knockdown of S100A11 increased the expression of E-cadherin and decreased the expression of Snail in ovarian cancer cells." (PMID 25780452, 2015). "The results revealed that knockdown of S100A11 caused an increase in E-cadherin and a decrease in Snail protein expression levels, suggesting that S100A11 affected the expression of E-cadherin and Snail in ovarian cancer cells." (PMID 25780452, 2015). "In order to silence the expression of S100A11 in ovarian cancer cells, HO8910 cells were transfected with S100A11 shRNA (sh), and three stable cell clones (sh#1, sh#2 and sh#3) were isolated by G418 selection." (PMID 25780452, 2015). "In the present study, the expression levels of S100A11 were found to be significantly increased in ovarian cancer cells." (PMID 25780452, 2015). "Collectively, these results indicated that S100A11 was able to promote the growth, invasion and migration of ovarian cancer cells." (PMID 25780452, 2015).